CKMT1A (creatine kinase, mitochondrial 1A)
Description:
Reversibly catalyzes the transfer of phosphate between ATP and various phosphogens (e.g. creatine phosphate). Creatine kinase isoenzymes play a central role in energy transduction in tissues with large, fluctuating energy demands, such as skeletal muscle, heart, brain and spermatozoa.
Synonyms: Mia-CK; U-MtCK; CKMT1
Tractability: Small molecule: a structure with a bound ligand is known; it has a high-quality binding pocket. Antibody: UniProt places it where antibodies can reach, with medium confidence.
Target class: Enzyme; Transferase
Gene: Protein-coding gene on chromosome 15 (43,692,886 to 43,702,501, forward strand). Ensembl gene ENSG00000223572.
Subcellular location: Mitochondrion inner membrane
Pathways (Reactome):
Metabolism: Creatine metabolism
Gene Ontology:
Molecular function: protein binding; creatine kinase activity; catalytic activity; kinase activity; phosphotransferase activity, nitrogenous group as acceptor; transferase activity, transferring phosphorus-containing groups
Biological process: phosphocreatine biosynthetic process
Cellular component: mitochondrion; mitochondrial inner membrane
Genetic constraint (gnomAD): Loss-of-function variants: 18 observed, 17.49 expected, observed/expected ratio (o/e) 1.03, 90% interval 0.71 to 1.52. The upper end of that interval is the gene's LOEUF score, 1.52, which puts it in group 6 of 6, group 1 being the genes least tolerant of losing a copy. Missense variants: 128 observed, 189.08 expected, observed/expected ratio (o/e) 0.68, 90% interval 0.59 to 0.78. Synonymous variants: 55 observed, 67.2 expected, observed/expected ratio (o/e) 0.82, 90% interval 0.66 to 1.02.
Homologues: Orthologues: rabbit CKMT1B (98% identical), mouse Ckmt1 (97% identical), rat Ckmt1 (97% identical), tropical clawed frog ckmt1b (84% identical), zebrafish ckmt1 (81% identical), Drosophila melanogaster Argk1 (38% identical), Caenorhabditis elegans F46H5.3 (37% identical), Caenorhabditis elegans F32B5.1 (36% identical), Caenorhabditis elegans W10C8.5 (36% identical), Drosophila melanogaster Argk2 (35% identical), Caenorhabditis elegans argk-1 (34% identical), Drosophila melanogaster CG4546 (34% identical), and 2 more. Paralogues in human: CKMT1B (100% identical), CKMT2 (79% identical), CKB (61% identical), CKM (59% identical).
Diseases named in the same sentence as CKMT1A in open-access papers:
CKMT1A is named in the same sentence as 32 diseases in open-access papers, as found by Europe PMC text mining. Sharing a sentence is not in itself a finding about the gene and the disease. The quoted sentences say what the papers report.
hepatocellular carcinoma (8 papers, 2020 to 2025). A malignant tumor that arises from hepatocytes. "Chronic hepatitis B virus induced the upregulation of lncRNA n335586, and the overexpression of n335586 promoted the expression of host CKMT1A by competitive binding to miR-924 to promote the migration and invasion of hepatocellular carcinoma cells." (PMID 40488465, 2025). "In the context of hepatitis B virus (HBV) infection, lncRNA n335586 potentiates the expression of host gene CKMT1A by competitively banding miR-924, thereby inducing the migration and invasion of hepatocellular carcinoma (HCC) cells." (PMID 37691924, 2023). "An axis comprising of lncRNA n335586/miR-924/CKMT1A is reported in metastasis of hepatocellular carcinoma cells." (PMID 34181336, 2021). "For example, lncRNA FAL1 promotes cell proliferation and migration by acting as a ceRNA of miR-1236 in hepatocellular carcinoma cells; lncRNA n335586/miR-924/CKMT1A axis contributes to cell migration and invasion in hepatocellular carcinoma cells." (PMID 33541391, 2021). "Recently, it has been reported that miR-924 has two targets in different diseases, including CKMT1A in hepatocellular carcinoma and α-defensin 5 (DEFA5) in inflammatory bowel disease." (PMID 33041671, 2020). "For example, lncRNA n335586 promoted hepatocellular carcinoma cells migration and invasion through facilitating the expression of its host gene CKMT1A by competitively binding miR-924." (PMID 32039833, 2020). "Interestingly, lncRNA n335586 promoted hepatocellular carcinoma cell migration and invasion through facilitating the expression of its host gene CKMT1A by competitively binding miR-924 in HBV-related hepatocellular carcinoma." (PMID 33041671, 2020). "Previous studies have reported that the over-expression of CKMT1A was related to acute myeloid leukemia (AML), breast cancer, hepatocellular carcinoma (HCC), neck squamous cell carcinoma and nasopharyngeal carcinoma." (PMID 35077462, 2022).
Obesity (3 papers, 2020 to 2025). Accumulation of substantial excess body fat. "Our RNA sequencing data showed that CKMT1A and B, futile cycle maintaining creatine kinases, were expressed higher in DN as compared to SC adipocytes and less abundant in those that had an obesity-risk genotype of the rs1421085 FTO locus." (PMID 32316277, 2020). "The genes CKMT1A and CKMT1B, which encode key mitochondrial creatine kinases and reported to be involved in UCP1-independent thermogenesis, were among those being significantly less expressed in FTO obesity-risk samples." (PMID 32316277, 2020).
breast carcinoma (2 papers, 2022). "According to previous reports, CKMT1A expression levels were increased in liver cancer, lung cancer and breast cancer cells, and this was consistent with our findings." (PMID 35705641, 2022). "Nevertheless, the only statistically significant difference in CKMT1A expression was observed between the primary HER2-positive breast cancer subtype and normal tissue." (PMID 35712500, 2022). "According to the TCGA database, CKMT1A is deleted in 40% of breast cancer patients, most of them are belonging to TNBC and Luminal A groups (71% and 22%, respectively)." (PMID 35712500, 2022). "In breast cancer, oncogenic HER2 induced phosphorylation of CKMT1A and then stabilized CKMT1A to promote cancer cell proliferation." (PMID 35705641, 2022).
endometrial carcinoma (2 papers, 2022). A malignant tumor arising from the epithelium that lines the cavity of the uterine body. "The “mutations” type of CKMT1A accounted for the vast majority of alterations in Endometrial Carcinoma cases." (PMID 35705641, 2022). "Association between CKMT1A expression and clinicopathological features of patients with endometrial cancer." (PMID 35077462, 2022). "Moreover, both Kaplan-Meier survival analysis and log-rank analysis were carried out to demonstrate that the higher levels of CKMT1A expression were closely associated with the lower chance of survival for the patients with endometrial cancer." (PMID 35077462, 2022). "In order to further explore the clinical significance of the expression of CKMT1A in patients with endometrial cancer, the association between the expression of CKMT1A and various clinical features was investigated using real-time quantitative PCR in 39 endometrial cancer patients." (PMID 35077462, 2022). "As expected, CKMT1A expression levels related to the prognosis of endometrial cancer as well as a higher level of CKMT1A demonstrated poorer prognosis than in patients with lower levels of expression (P = 0.0128)." (PMID 35077462, 2022). "More importantly, Human Protein Atlas and quantitative PCR confirmed the differences in expression of CKMT1A in endometrial cancer samples at different FIGO stages." (PMID 35077462, 2022). "Next, 39 endometrial cancer samples were divided into “high” and “low” according to the CKMT1A median level of 0.008315392." (PMID 35077462, 2022). "The results suggested that CKMT1A is up-regulated in endometrial cancer tissue and down-regulated in the endometrium (P = 0.007)." (PMID 35077462, 2022). "More importantly, a multivariate Cox’s regression analysis suggested that CKMT1A level (HR = 0.388; P = 0.0001) and the difference of stage (HR = 1.174; P = 0.045) were independent prognostic factors for the OS of patients with endometrial cancer." (PMID 35077462, 2022). "CKMT1A expression was high in endometrial cancer patients at advanced stages, low histological differentiation and poor prognosis (P<0.0001; P = 0.006)." (PMID 35077462, 2022). "Essentially, the obtained results imply that CKMT1A expression plays a significant role in predicting tumor progression in patients with endometrial cancer." (PMID 35077462, 2022). "To investigate the clinical significance of CKMT1A expression in patients with endometrial cancer, we used the Human Protein Atlas database to confirm the histological level of CKMT1A." (PMID 35077462, 2022). "The results revealed that CKMT1A may be a key molecule in endometrial cancer, which is known to have a close relation with metabolic diseases." (PMID 35077462, 2022). "A higher expression of CKMT1A was consistently found to be associated with the FIGO stage, histological differentiation and abnormal CA125 value, which signified a poor prognosis for patients with endometrial cancer." (PMID 35077462, 2022). "The expression of CKMT1A may be a valuable adjuvant parameter in the prognosis of patients with endometrial cancer and provides a potential future therapeutic strategy." (PMID 35077462, 2022). "Furthermore, we verified the clinical significance of CKMT1A expression levels in Human Protein Atlas and clinical endometrial cancer samples." (PMID 35077462, 2022). "Therefore, a further research into CKMT1A was conducted, which showed its involvement in tumor processes of endometrial cancer and contributed to a more unbeneficial prognosis." (PMID 35077462, 2022). "Through survival analyses, we found that CKMT1A may be a poor prognostic factor in the overall survival of endometrial cancer patients." (PMID 35077462, 2022). "In summary, this study shows that CKMT1A is a newly identified essential tumor progression regulator of endometrial cancer, which may give rise to novel therapeutic strategies in the management of endometrial cancer patients to prolong its prognosis and prevent tumor progression." (PMID 35077462, 2022).
endometrial carcinoma (continued). "Aligning with similar results showing that CKMT1A lowers the apoptosis rate and promotes proliferation and migration in nasopharyngeal carcinoma and neck squamous cell carcinoma, so that we deduced that CKMT1A plays an essential role in regulating endometrial cancer progression." (PMID 35077462, 2022). "Moreover, the CKMT1A alterations of the “amplification” type of CNA were mostly found in Pleural Mesothelioma and Endometrial Carcinoma cases, with the frequency of ~ 1%." (PMID 35705641, 2022).
liver cancer (2 papers, 2021 to 2022). An epithelial or non-epithelial malignant neoplasm that arises from the liver. "Based on the datasets of the Kaplan–Meier plotter covering liver cancer cases in GEO data, we found an opposite result, namely lower CKMT1A expression relates to poorer RFP (P < 0.05)." (PMID 35705641, 2022). "Further mechanistic studies have shown that lncRNA n335586 promotes expression of its host gene CKMT1A by competitively binding with miR-924, thereby promoting the migration and invasion of liver cancer cells." (PMID 34869051, 2021). "However, a low CKMT1A expression level was associated with poor OS (P = 0.0019), FP (P < 0.001), and PPS (P = 0.018) prognosis for gastric cancer and poor RFS (P = 0.018) prognosis of liver cancer." (PMID 35705641, 2022). "In summary, the n335586/miR-924/CKMT1A axis is involved in the migration and invasion of liver cancer cells, which may help to explain the pathogenesis of HBV-related liver cancer." (PMID 34869051, 2021).
colon adenocarcinoma (1 paper, 2022). "And the expression of CKMT1A in the tumor tissues of COAD (Colon adenocarcinoma) (P < 0.001), GBM (Glioblastoma multiforme) (P < 0.001), KIRC (Kidney renal clear cell carcinoma) (P < 0.001), THCA (Thyroid carcinoma) (P < 0.05) was significantly lower than the corresponding control tissues." (PMID 35705641, 2022).
glioma (1 paper, 2022). A benign or malignant brain and spinal cord tumor that arises from glial cells (astrocytes, oligodendrocytes, ependymal cells). "The CKMT1A expression level was significantly lower in tumor tissues of LGG (Brain lower grade glioma) (P < 0.05)." (PMID 35705641, 2022). "However, in oral cancer, prostate cancer and glioma, the expression level of CKMT1A was lower in tumor tissues than that in normal tissues." (PMID 35705641, 2022).
lung carcinoma (1 paper, 2022). "Furthermore, we explored the association between genetic alteration of CKMT1A and the clinical survival prognosis of lung cancer." (PMID 35705641, 2022).
nasopharyngeal carcinoma (1 paper, 2022). A carcinoma arising from the nasopharyngeal epithelium. "CKMT1A can reduce the arrest of the G2/M phase cell cycle, enhance colony formation rates, lower the apoptosis rate and c-PARP level, and elevate STAT3 phosphorylation levels via CRISPR/Cas9 system in nasopharyngeal carcinoma." (PMID 35077462, 2022).
non-small cell lung carcinoma (1 paper, 2022). A group of at least three distinct histological types of lung cancer, including non-small cell squamous cell carcinoma, adenocarcinoma, and large cell carcinoma. "Non-Small Cell Lung Cancer cases with altered CKMT1A showed a poorer overall survival." (PMID 35705641, 2022).
oral cancer (1 paper, 2022). "However, in oral cancer, prostate cancer and glioma, CKMT1A expression level in tumor tissues is lower than that in the normal tissues." (PMID 35705641, 2022).
ovarian carcinoma (1 paper, 2022). A malignant neoplasm originating from the surface ovarian epithelium. "In contrast, a high expression level of CKMT1A was related to a poor PPS (P = 0.0092) prognosis for ovarian cancer." (PMID 35705641, 2022).
ovarian serous cystadenocarcinoma (1 paper, 2022). A malignant serous cystic epithelial neoplasm arising from the ovary. "The CKMT1A expression level was significantly higher in tumor tissues than in the corresponding controls in OV (Ovarian serous cystadenocarcinoma), TGCT (Testicular germ cell tumors) and UCS (Uterine carcinosarcoma) (all P < 0.05)." (PMID 35705641, 2022).
renal oncocytomas (1 paper, 2017). "Mitochondrial creatine kinase S-type (CKMT2, 57- fold) and U-type (CKMT1A, 18-fold) are responsible for the energy and metabolite transfer between mitochondria and cytoplasm (i.e. the creatine phosphate shuttle), and were increased in renal oncocytomas." (PMID 29285300, 2017).
cancer (9 papers, 2016 to 2024). A tumor composed of atypical neoplastic, often pleomorphic cells that invade other tissues. "CKMT1A expression was negatively correlated with the infiltration of cancer-associated fibroblasts in most tumors." (PMID 35705641, 2022). "High expression of CKMT1A was associated with a good prognosis of overall survival (OS) for cancers of KIRP (P = 0.035), LGG (P < 0.001) and UVM (P = 0.0081) in the TCGA project." (PMID 35705641, 2022). "For example, the expression level of CKMT1A in LGG was negatively correlated with the infiltration level of cancer-associated fibroblasts (cor = − 0.447, P = 7.91e−25) based on the XCELL algorithm." (PMID 35705641, 2022). "Furthermore, we explored the association between genetic alteration of CKMT1A and the clinical survival prognosis in different types of cancers." (PMID 35705641, 2022). "Analysis of mRNA level for all examined groups revealed that in both cancer cell lines CKMT1A was downregulated compared to MCF10A cells." (PMID 35712500, 2022). "In this study, we aimed to explore the role of human CKMT1A (NM_001015001.2 for mRNA or NP_001015001.1 for protein) in cancer." (PMID 35705641, 2022). "To determine the expression level of CKMT1A, we used the TIMER2 web tool to analyze the CKMT1A in various cancer types of TCGA." (PMID 35705641, 2022). "In this study, we conducted a pan-cancer analysis of CKMT1A based on the data of the TCGA project and GEO database." (PMID 35705641, 2022). "We analyzed gene expression, survival prognosis, genetic alteration, immune infiltration, and cellular pathway, to explore the potential mechanisms of CKMT1A across different cancers." (PMID 35705641, 2022). "In our study, we found that CKMT1A was highly expressed in most cancer, but was lowly expressed in COAD, GBM, KIRC, THCA and LGG compared to corresponding control tissues." (PMID 35705641, 2022). "Cancer is a metabolic disease, and the function of CKMT1A in mitochondria plays an important role in the energy demand transformation process." (PMID 35705641, 2022). "To further explore the molecular function of the CKMT1A gene in cancer, we attempted to screen out the CKMT1A correlated genes and CKMT1A-interacting proteins for subsequent pathway enrichment analyses." (PMID 35705641, 2022). "The different expression patterns of CKMT1A in various tumors implied it seemed to have opposite effects on the biological function of cancer." (PMID 35705641, 2022). "According to the expression median levels of CKMT1A, we divided the cancer cases into high-expression and low-expression groups." (PMID 35705641, 2022). "Considering the specific mechanism by which CKMT1A regulates cell function in cancer is not well understood, we seek to perform a pan-cancer analysis to fully understand its function in various tumor types." (PMID 35705641, 2022). "Taken together, our pan-cancer analysis of CKMT1A provided a comprehensive understanding of CKMT1A in gene expression, genetic alteration, clinical prognosis, immune cell infiltration and pathway analysis." (PMID 35705641, 2022). "CKMT1A exerts different functions because cancer cells have different genetic backgrounds and are regulated by multiple factors and the combined effect of microenvironment." (PMID 35705641, 2022). "In recent years, several studies have suggested that mitochondrial creatine kinase 1A (CKMT1A) plays a key role in various cancer types." (PMID 35705641, 2022). "In this study, we performed a series of bioinformatics analysis of CKMT1A regarding its expression, gene function, genetic alteration, immune infiltration and survival prognostic in 33 cancer types based on TCGA, GEO and CPTAC databases." (PMID 35705641, 2022). "CKMT1A was highly expressed in most types of cancers and there was a significant correlation between CKMT1A expression and the prognosis of patients for certain tumors." (PMID 35705641, 2022).